ALDH1A2 (aldehyde dehydrogenase 1 family member A2)
Diseases named in the same sentence as ALDH1A2 in open-access papers (continued):
Sharing a sentence is not in itself a finding about the gene and the disease.
type 1 diabetes (1 paper, 2018). "In a type 1 diabetes rat model, rats presented lower plasma retinol levels and higher hepatic retinol levels compared to the control rats, as well as lower and higher expression of ALDH1A1 and ALDH1A2, respectively." (PMID 30373117, 2018).
cancer (47 papers, 2012 to 2025). A tumor composed of atypical neoplastic, often pleomorphic cells that invade other tissues. "In the past, the promoter hypermethylation of ADHFE1 or ALDH1A2 was identified as a common issue in cancers and served as a risk factor with a poor prognosis." (PMID 32238162, 2020). "These CTCs expressing IGFBP5 also had increased expression of stem cell associated genes aldehyde dehydrogenase 1A2 (ALDH1A2) and Kruppel-like factor 4 (Klf4), which could indicate a cancer stem-like cell phenotype, a state thought to modulate the ability of cancer cells to seed new tumors." (PMID 36465383, 2022). "The paracrine immune mechanism of atRA also explains why ectopic expression of ALDH1a2 or ALDH1a3 in ALDH-negative cancer cells is often growth suppressive." (PMID 39133222, 2024). "Complementing tumor ALDH1a3, ALDH1a2 is found in the cancer stroma, such as the immunoregulatory mucosal myeloid regulatory DCs found in lung cancer patients or the M2 macrophages in glioblastoma that promote tumor tolerance." (PMID 39133222, 2024). "Two cancer-risk mutations found in ALDH1A1 (R395H) and ALDH1A2 (R412W) show a similar structural location at the NAD(P)+ binding region." (PMID 37373306, 2023). "We therefore evaluated the expression of a panel of epithelial (KRT5, 7, 8, 18, and CDH1), mesenchymal (VIM, FN1, SNAI1, TWIST1, COL1A1, and PRRX1), and cancer stem cell (ALDH1A2, ALDH7A1, CD44, and CCND1) markers in all samples." (PMID 36980717, 2023). "Our results also demonstrate that ALDH1A2, a tumor suppressor gene that has a hypermethylated promoter in numerous cancers, is similarly downregulated in CTB differentiation/invasion." (PMID 34121116, 2021). "A pan-cancer analysis with 10,967 tumor samples in 32 TCGA cohorts revealed that a low frequency of ALDH1A2 (1.4%), OSR2 (5%), GRIA4 (3%), GATA4 (4%), and IRX4 (5%) was genetically altered." (PMID 34745985, 2021). "Here, we found that GBP5 knockdown decreased several chemotherapy resistance-associated cancer stemness markers such as ALDH1A1, ALDH1A2, CD44, CD166, and ABCG2." (PMID 34439200, 2021). "Cancer stem cell markers ALDH1A2, ALDH7A1, CD44, and CCND1 were also upregulated in CTCs compared to HDs." (PMID 32998338, 2020). "Our results indicated that knockdown of UBE2C decreased the expression levels of these cancer stemness markers including ALDH1A2, CD44, CD166 and EpCAM in both Ca9-22 and SAS cells." (PMID 32899896, 2020). "ALDH1A2 is expressed at very low level in all types of cancer, whereas ALDH1B1, ALDH3B1, and ALDH5A1 are expressed at medium level universally, implying a ubiquitous role of these isoforms." (PMID 30220009, 2019). "Even without the exact mechanisms being fully understood yet, we are able to use the putative role of ALDH1A2 in cancer to derive a core gene set from ALDH1A2-interacting partners, using available literature and curated databases." (PMID 28361034, 2017). "In PCa, a previous study has found hypermethylation of ALDH1A2 in cancer cell lines subjected to treatment with the chemotherapeutic agent 5-aza-2′-deoxycytidine." (PMID 28361034, 2017). "In addition, ALDH1A2, CARD11 and CTLA4 are implicated in cancer immunity and can be useful prognostic biomarkers in some cancer types." (PMID 39351147, 2024). "Low expression of ALDH1A2 in cancers is always due to its promoter hypermethylation." (PMID 36694633, 2023). "In this study, the expression of ALDH1A2 decreased in patients with EBC, suggesting that ALDH1A2 may play different regulatory roles in different cancers." (PMID 35132081, 2022). "In the MCF7 epithelial carcinoma cell line, Kcnk5b induced ALDH1a2, PEA3, and MSX1." (PMID 33830014, 2021). "ADHFE1 and ALDH1A2 have been reported to be downregulated and hypermethylated in cancers." (PMID 32238162, 2020). "This suggests that ALDH1A2 is a novel hypermethylated gene in cancer." (PMID 31615043, 2019). "The biology of ALDH1A2 is complex, and its roles in cancer are being increasingly explored." (PMID 28361034, 2017).
cancer (continued). "The involvement of stem cell-like cancer cells in chemoresistance is reinforced by the finding that ALDH1A2 is one of the most upregulated genes in chemoresistant cells and that the NSCLC subset with an augmented ALDH activity (ALDHhigh) features a greater chemoresistance." (PMID 26181204, 2015). "The isoforms aldehyde dehydrogenase 1 family member A2 (ALDH1A2), 2 family member (ALDH2), ALDH3A2, and 9 family member A1 (ALDH9A1) were downregulated in all cancers studied." (PMID 40923024, 2025). "Several isoforms of the ALDH1 family (ALDH1A1, ALDH1A2, ALDH1A3, ALDH1B1, ALDH1L1, and ALDH1L2) are used as cancer stem cell markers in a variety of cancers." (PMID 34680942, 2021). "More studies will be focused on investigating how UBE2C regulating these cancer markers including ALDH1A2, CD44, CD166 and EpCAM and the relationship between these cancer markers for cancer stemness in vitro." (PMID 32899896, 2020). "Aldehyde dehydrogenase (ALDH) isoforms, such as ALDH1A1 or ALDH1A2, have been reported as CSC markers in several cancer types." (PMID 32726929, 2020). "For example, ALDH1A2, ALDH2, ALDH3A2 and ALDH9A1 were downregulated in all tumors among the 5 cancer types, whereas ALDH1B1, ALDH1L2 and ALDH18A1 were most upregulated in tumor parts." (PMID 29426835, 2018). "Lastly, miR-708-5p suppressed expression of various cancer stem cell markers (CD117, CD34, CD44, octamer-binding transcription factor 4 [OCT4], Aldehyde Dehydrogenase 1 Family Member A2 [ALDH1A2], and NANOG) in A549 and PG cells." (PMID 29050362, 2017). "Other markers of cancer stem cells in NB also have been reported, and they include CD114, Frizzled receptor 6, ALDH1A2, as well as the ability to exclude Hoechst 3334239–47." (PMID 29203817, 2017). "ALDH1 has three main isotypes, ALDH1A1, ALDH1A2, and ALDH1A3, and is a marker of normal tissue stem cells (SC) and cancer stem cells (CSC), where it is involved in self-renewal, differentiation and self-protection." (PMID 26783961, 2016). "The subfamily of aldehyde dehydrogenases 1 (ALDH1) isoenzymes, which comprises ALDH1A1, ALDH1A2, and ALDH1A3, is involved in the synthesis of retinoic acid, and has been identified as functional stem cell markers in diverse cancers." (PMID 27724856, 2016). "A very recent study performing high-throughput analysis of NMIBC revealed a Class 2 tumor that associates with progression, these Class 2 tumors enriched for cancer stem cell markers such as ALDH1A1, ALDH1A2, PROM1, NES and THY1." (PMID 27655672, 2016). "Whether the paired cancer versus normal cells investigated have differentiated to the same degree is also important because the levels of expression of ALDH1A1, ALDH1A2 and ALDH1A3 change during development, and, for example, parallel rat nephron development." (PMID 36768694, 2023). "However, no cancer-type specific expression preference of ALDH1A2, ALDH1B1, ALDH3B1, and ALDH5A1 has been observed." (PMID 30220009, 2019). "Taken together, these data suggest that ALDH1A2 and ALDH1A3 generate atRA in human cancer cells and primary tumors, but this does not appear to affect tumorigenesis or growth in immunodeficient mice." (PMID 41210994, 2025). "Several of these isoforms have been reported by other groups to be involved in ALDEFLUOR assay, namely ALDH1A1, ALDH1A2, ALDH1A3, and ALDH2, while the other five ones have seldom been described and their role in cancer have not yet been explored in detail." (PMID 30220009, 2019).
tumor (38 papers, 2014 to 2025). "ALDH1A2 immunoreactivity was associated with an early tumor stage (p < 0.001) and serous cell type (p < 0.001)." (PMID 31615043, 2019). "Finally, the impact of ALDH1A2 loss-of-function on tumor growth was investigated in vivo by orthotopic injection of stable FaDu-shALDH1A2 or FaDu-mock control cells in the floor of the mouth of nude mice." (PMID 26634247, 2015). "Other studies showed that inhibition of ALDH1a2 reduces Tregs in lymphomas and melanomas, leading to decreased tumor size." (PMID 39133222, 2024). "The intensive expression of KIF26A and ALDH1A2 on smooth muscle cells suggests their potential involvement in tumor progression." (PMID 39440060, 2024). "Box whisker plots showed that promoter DNA methylation levels of ALDH1A2 in tumor clinical stage IV were significantly elevated than any other subgroup with stage I/II/III." (PMID 34745985, 2021). "ALDH1A2 has previously been identified as a candidate tumor suppressor and its downregulation accelerates an epithelial-to-mesenchymal transition, an important component of CTB invasion." (PMID 34121116, 2021). "ALDH1A1 was expressed in six out of nine tumors; ALDH1A2 was also expressed in six out of nine tumor samples, and ALDH1A3 was present in only one out of nine tumors examined." (PMID 34572134, 2021). "In line with the previous studies, our results showed that the expression of ALDH1A2 at an advanced stage is lower than that at an early tumor stage." (PMID 34745985, 2021). "The expression of ALDH1A2 at an advanced stage (stage III/IV) is lower than that at an early tumor stage (stage I/II)." (PMID 31615043, 2019). "A possible mechanism for the tumor suppressive effect of methylated ALDH1A2 can be mediated through RA signaling." (PMID 31615043, 2019). "The Kaplan–Meier plots demonstrated that the patients with lower ALDH1A2 expression, as well as patients with advanced tumor stage (stage III/IV), displayed shorter disease-free (p < 0.001) and overall (p < 0.001) survival." (PMID 31615043, 2019). "The impact of ALDH1A2-RAR signaling on tumor-relevant processes was addressed in established tumor cell lines and in an orthotopic mouse xenograft model." (PMID 26634247, 2015). "shRNA-mediated silencing of ALDH1A2 protein expression was confirmed in vitro by Western immunoblot analysis with whole-cell lysate and in vivo by immunohistochemical staining on tumor sections." (PMID 26634247, 2015). "The inverse correlation between ALDH1A2 and vimentin expression in tumor cells was further supported in a mouse xenograft model in vivo and tumor sections from OPSCC patients." (PMID 26634247, 2015). "Although such data point to a putative tumor suppressor function of ALDH1A2 in the pathogenesis of several epithelial cancers, the causal link between loss of ALDH1A2 function and molecular mechanisms of treatment failure have not been addressed so far." (PMID 26634247, 2015). "Among the stromal genes, we note that the everolimus+SNX631 combination upregulated an angiogenesis inhibitor Tnmd and putative tumor-suppressive proteins Acaca, Per3, and Ccl11, whereas Aldh1a2, a tumor stimulating stromal factor, was downregulated by the combination." (PMID 39541354, 2024). "Interestingly, ALDH1A2 expression is virtually undetectable in GBM cells in culture, which further supports that the tumor microenvironment influences the expression of ALDH1A2 in GBM tumor cells." (PMID 34572134, 2021). "As therapeutic interventions affect the tumor microenvironment, we next asked whether the expression of ALDH1A2 was changed upon tumor recurrence." (PMID 34572134, 2021). "It is possible that one or more of these cell populations could be responsible for the increase in ALDH1A2 expression upon tumor recurrence, though this has yet to be fully investigated." (PMID 34572134, 2021). "Therefore, we again stained for ALDH1A2 immunoreactivity in 10 GBM tumor specimens and 8 cell lines and found that ALDH1A2 was expressed quite prominently in GBM specimens." (PMID 34572134, 2021).
tumor (continued). "Indeed, compelling evidence has emerged in recent years, supporting a tumor-suppressive role of ALDH1A2." (PMID 31615043, 2019). "It has been reported that ALDH1A2 is a candidate tumor suppressor gene in prostate cancer." (PMID 30944378, 2019). "Reduced expression of ALDH1A2 also correlated with shorter recurrence-free survival of patients, suggesting that ALDH1A2 may in fact be a tumor suppressor gene for PCa." (PMID 28361034, 2017). "Based on these findings, we speculate that a subgroup of HNSCC patients at high risk for treatment failure under currently established therapeutic regimens might benefit from an adjuvant treatment with retinoids to restore ALDH1A2-RAR signaling in tumor cells." (PMID 26634247, 2015). "Functionally, ALDH1A2 expression and activity in tumor cell lines were related to RA levels." (PMID 26634247, 2015). "In contrast to Aldh1a2, Klf4 is expressed in epithelial components of the primary tumor." (PMID 25242334, 2014). "Therefore, ALDH1A2 might function as a potential tumor suppressor protein in the process of ZEA 3.0 treatment." (PMID 36287961, 2022). "For example, ALDH1A2 was positively correlated with CPA6 (r = 0.5, p < 0.0001) in tumor tissues, while in normal tissues, ALDH1A2 expression was negative (r = −0.63, p < 0.0001) correlated with CPA6." (PMID 41081583, 2025). "Further in line with the immunosuppressive characteristics of tumor-induced CD14+ cDC2s is the increased expression of aldehyde dehydrogenase 1 family, member A2 (ALDH1A2)." (PMID 40789452, 2025). "Luciferase imaging of the RARE-Luc reporter then revealed that both ALDH1A2 and ALDH1A3 synthesize atRA in tumor cells growing in vivo." (PMID 41210994, 2025). "Retinaldehyde dehydrogenase-2 (ALDH1A2) is highly expressed in M2 GAMs in patients with recurrent GBM, whose expression increases with tumor recurrence at the gene and protein level." (PMID 37218976, 2023). "In this study, we identified and evaluated the expression of ALDH1A2 in the GBM microenvironment, and especially in M2 GAM, though it is also expressed in reactive astrocytes and multinucleated tumor cells." (PMID 34572134, 2021). "In the future, it will be important to understand how the expression of ALDH1A2 in reactive astrocytes and multi-nucleated tumor cells affects the GBM tumor cells and the microenvironment." (PMID 34572134, 2021). "Despite aberrant promoter hypermethylation of ALDH1A2, OSR2, GATA4, and GRIA4 have already been reported in several human tumor cell lines or tumor tissues." (PMID 34745985, 2021). "As expected, differential expression analysis revealed that the levels of ALDH1A2 and OSR2 were significantly reduced in the tumor tissues as compared to the normal tissues." (PMID 34745985, 2021). "Differential expression analysis revealed that the levels of ALDH1A2 and OSR2 were significantly reduced in the tumor tissues as compared to the normal tissues." (PMID 34745985, 2021). "DNMT3B is not only differentially expressed in tumor tissues, but also has significant correlation with ADHFE1 and ALDH1A2 expression." (PMID 32238162, 2020). "Multivariate analysis showed that ALDH1A2 expression (p = 0.012), FIGO stage (p < 0.001), and tumor grade (p = 0.032) were independent prognostic factors for disease-free survival." (PMID 31615043, 2019). "This indicates that ALDH1A2+ cells make up a subpopulation of cells in the GBM tumor microenvironment and do not encompass all M2 GAM." (PMID 34572134, 2021). "Reactive astrocytes, non-activated microglia, and multi-nucleated tumor cells also stained for ALDH1A2." (PMID 34572134, 2021). "Having determined that cells within the GBM tumor microenvironment express ALDH1A2, we wanted to examine whether GBM cells influence the expression of ALDH1A2 in monocytic cells." (PMID 34572134, 2021). "In LGG, there is a trend toward increased ALDH1A2 expression upon tumor recurrence, though this did not achieve statistical significance." (PMID 34572134, 2021).
tumor (continued). "Specifically, ALDH1A2 is expressed in macrophages and non-activated microglial cells, and also multi-nucleated tumor cells and reactive astrocytes." (PMID 34572134, 2021). "Our results suggest the hypothesis that other cell types may be responsible for this increase in ALDH1A2 expression, as cells which co-stain for GFAP, a tumor cell, and reactive astrocyte markers were found in GBM tumors (data not shown)." (PMID 34572134, 2021). "In tumor immunity, the ALDH1 family (including ALDH1A1, ALDH1A2, and ALDH1A3) converts retinal to RA, which promotes the induction, function and stability of regulatory T cells, leading to immune tolerance that compromises tumor immunity." (PMID 32140062, 2020). "Moreover, high ALDH1A2 expression in NB correlates with poor survival, suggesting a role for this ALDH1 isoenzyme in NB tumor aggressiveness." (PMID 27724856, 2016). "In this study, we first confirmed the enrichment of ALDH1A2 and ALDH1A3 expression during NB TICs selection in one PDX tumor (NB1), as well as in two distinct cell lines, the NB1-C cells derived from the NB1 PDX tumor, and/or the I-type SK-N-Be2c cell line." (PMID 27724856, 2016). "To first test that ALDH1A3 can generate atRA in tumor cell lines, we took advantage of the finding that the ALDH1A3-negative cell line MCF7 was sensitive to atRA, and therefore, we ectopically expressed ALDH1A3 along with the related isoforms ALDH1A1 and ALDH1A2 to create stable MCF7 cell lines." (PMID 41210994, 2025). "However, ATRA, which is lipophilic, passes freely between cells and normal ovarian surface epithelial cells expressed ALDH1A2 and produced ATRA, which may be made available to the patients’ tumour cells." (PMID 36768694, 2023). "However, expression in the NAU was predicted to be driven by ALDH1A2 and MFAP4 —genes that are both notoriously downregulated in other genitourinary malignancies compared to normal samples, likely suggesting tumor-suppressive roles." (PMID 35626146, 2022). "Moreover, immunohistochemical analysis of the representative specimens of patients with OSCC demonstrated that the expression of ADHFE1 and ALDH1A2 expression was greater in nontumor squamous epithelium than in tumor tissues." (PMID 32238162, 2020). "Additional studies have reported that ALDH1A1, ALDH7A1, ALDH2 and/or ALDH1A2 are responsible for driving Aldefluor® activity in other tumor types, indicating that the ALDH isoform(s) responsible for Aldefluor® activity may be tumor-specific." (PMID 28937653, 2017). "In contrast, ALDH1A2 mRNA expression was strongly increased, in early steps of the TIC selection process (s1-s2) and remained elevated in later NS passages (s3-s4) in the I-type SK-N-Be2c cell line, as well as in the NB1 PDX tumor and the related NB1-C cell line." (PMID 27724856, 2016). "Of interest, neither CD163 nor ALDH1A2 were detected in normal brain sections, suggesting that ALDH1A2 expression takes place within the GBM tumor microenvironment and is not a function of the non-diseased brain." (PMID 34572134, 2021). "We demonstrated that the enzymatic product of ALDH1A2, retinoic acid (RA), modulated the expression and activity of MMP-2 and MMP-9 in macrophages, but not in GBM tumor cells." (PMID 34572134, 2021). "Interestingly, ALDH1A2 was largely absent in established GBM cell lines and moderately expressed in patient-derived low-passage cell lines, suggesting that the expression of ALDH1A2 in established GBM tumor cells is not preserved under in vitro culture conditions." (PMID 34572134, 2021).